PSMA7 (proteasome 20S subunit alpha 7)
Diseases named in the same sentence as PSMA7 in open-access papers (continued):
Sharing a sentence is not in itself a finding about the gene and the disease.
hepatitis B (1 paper, 2005). "Three other antigens (SR140 protein, SFRS2IP, RNPC2) may be involved in the regulation of alternative mRNA splicing, PSMA7 is related to hepatitis B and hepatitis C viral replication, and the remaining 12 antigens have no known association with cancer or hepatitis B or hepatitis C." (PMID 15756260, 2005).
Intellectual disability (1 paper, 2013). "A de novo heterozygous 335C-A transversion in PSMA7, resulting in an A112D mutation, was identified in a male patient with severe intellectual disability, suggesting that PSMA7 may be a candidate intellectual-disability gene." (PMID 24490108, 2013).
intestinal cancer (1 paper, 2017). "In addition, PSMA7 is reported to be associated with intestinal inflammation and is associated with intestinal cancer metastasis." (PMID 28523434, 2017).
kidney cancer (1 paper, 2017). Primary or metastatic malignant neoplasm involving the kidney. "PSMA7 was overexpressed in kidney cancer analyzed by Higgins and Yusenko's datasets." (PMID 27966459, 2017).
kidney chromophobe cell carcinoma (1 paper, 2017). "Compared with normal kidney tissue, PSMA1, PSMA3 and PSMA7 were upregulated in kidney chromophobe cell carcinoma, whereas PSMA5 was downregulated." (PMID 27966459, 2017).
liver cancer (1 paper, 2024). An epithelial or non-epithelial malignant neoplasm that arises from the liver. "Moreover, the upregulated transcript level of PSMA7 had a close link to poor OS and RFS while not PFS or DFS for liver cancer." (PMID 38321088, 2024).
lymphoid neoplasm (1 paper, 2024). A neoplasm composed of a lymphocytic cell population which is usually malignant (clonal) by molecular genetic and/or immunophenotypic analysis. "The amplified CNA of PSMA7 was related to worse DFI for BLCA and lymphoid neoplasm DLBC, but similar OS for CESC." (PMID 38321088, 2024).
male infertility (1 paper, 2023). The inability of the male to effect fertilization of an ovum after a specified period of unprotected intercourse. "PSMA8 deletion delays entry into the M phase by activating phase I proteins; a decrease in PSMA7 stops it at this stage and ultimately causes male infertility." (PMID 37239333, 2023).
melanoma (1 paper, 2017). A malignant, usually aggressive tumor composed of atypical, neoplastic melanocytes. "PSMA1, PSMA3 and PSMA7 were significantly associated with survival outcomes in melanoma patients." (PMID 27966459, 2017).
myeloid leukemia (1 paper, 2017). A clonal proliferation of myeloid cells and their precursors in the bone marrow, peripheral blood, and spleen. "Knockdown of PSMA7 in myeloid leukemia cell K562 resulted in a marked proliferation inhibition." (PMID 27966459, 2017).
Parkinson disease (1 paper, 2014). A progressive degenerative disorder of the central nervous system characterized by loss of dopamine producing neurons in the substantia nigra and the presence of Lewy bodies in the substantia nigra and locus coeruleus. "Parkin, an E3 ligase implicated in Parkinson disease (PD), interacts through its C-terminus IBR-RING with the C-terminal region of PSMA7, and it may function as an accessory protein for substrate presentation to the proteasome for degradation." (PMID 25534281, 2014).
prion disease (1 paper, 2022). A transmissible disease that is caused by a protein that is able to induce abnormal folding of normal cellular proteins, leading to characteristic spongiform brain changes, which are associated with neuronal loss without an inflammatory response. "C1QA, NCAM2 and PSMA7 were enriched in the prion disease pathway." (PMID 36277688, 2022).
prostate tumor (1 paper, 2016). "Notably, PSMA7, a subunit of the catalytic 20S core proteasome that potentiates AR-mediated transcription when overexpressed in prostate tumor cells, was enriched in the AS sample." (PMID 27365400, 2016).
psoriasis (1 paper, 2025). An autoimmune condition characterized by red, well-delineated plaques with silvery scales that are usually on the extensor surfaces and scalp. "We identified PSMA6, a reported genetic risk factor for the development of psoriasis and IBD52,53, PSMA7 (proteasome 20S subunit alpha), a biomarker of IBD54, and RPS3 (ribosome small 40S subunit) as potential LZTR1-interacting proteins, while only PSMA7 and RPS3 were validated through co-IP." (PMID 41162356, 2025).
scrapie (1 paper, 2014). A fatal disease of the nervous system in sheep and goats, characterized by pruritus, debility, and locomotor incoordination. "The downregulation of PSMA7 and UCHL1 genes and the positive association of PrPSc deposition with PSMB8 expression in both preclinical and clinical stages of natural scrapie in the LRS of sheep is in line with the impaired proteasome function described in prion diseases of the nervous system." (PMID 24450868, 2014). "The observed downregulation of PSMA7 and UCHL1 may facilitate prion conversion, implicating these genes in the pathogenic mechanism of the scrapie." (PMID 24450868, 2014). "Genes encoding proteins involved in molecular pathways that regulate protein misfolding (PSMA7, UCHL1 and PFDN2) were downregulated in scrapie-infected animals." (PMID 24450868, 2014).
Sepsis (1 paper, 2026). Sepsis is defined as life-threatening organ dysfunction caused by a dysregulated host response to infection. "In sepsis patients, higher plasma levels of PSMA7 and PSMB2 were associated with increased 90-day mortality and positively correlated with markers of liver injury and SOFA scores." (PMID 41939900, 2026).
thymoma (1 paper, 2024). A neoplasm arising from the epithelial cells of the thymus. "Finally, we discovered that cohorts with thymoma (THYM) harbored deep deletion of PSMA7 with the highest frequency (0.81%) but represented a minority of cancers." (PMID 38321088, 2024).
varicocele (1 paper, 2020). A condition characterized by the dilated tortuous veins of the spermatic cord with a marked left-sided predominance. "Nonetheless, proteins, such as CLGN, FTH1, MDH1, MIF, PPP3CA, SUCLA2, and PSMA7, involved in sperm function, apoptosis, and oxidative stress were present in a low and very low abundance in the unilateral and bilateral varicocele group, respectively." (PMID 32365753, 2020).
cancer (20 papers, 2005 to 2025). A tumor composed of atypical neoplastic, often pleomorphic cells that invade other tissues. "Distinguishing from the previous pan-cancer research focusing on the prognostic values of PSMA7 59, we further investigated the underlying mechanism linking high PSMA7 expression to poor prognosis." (PMID 38321088, 2024). "Thanks to these interactions, PSMA7 is implicated in diverse cancer-related cellular activities, including transcription control, immunologic reaction, stress responses, cell cycle regulation, cellular differentiation, proliferation, and apoptosis." (PMID 38321088, 2024). "Moreover, we found that PSMA7 was significantly essential for tumor cell viability in the CRISPR-mediated loss of function screens of 1095 cancer cell lines." (PMID 38321088, 2024). "Taken together, our study supported PSMA7 as the crucial gene at the 20q amplification hotspot and a potential new biomarker for the diagnostic testing, prognostic evaluation, and molecular therapeutic development of human cancers." (PMID 38321088, 2024). "Among the hypoxia-related molecules, MRPS17, CDCHD2, PSMA7, and MIF consistently demonstrated a positive correlation with PEBP1/STK11 co-expression across all cancer types in which a significant association was observed." (PMID 40806276, 2025). "Next, we employed GEPIA2 to investigate the prognostic significance of PSMA7 overexpression across numerous cancers according to the TCGA and GEO projects." (PMID 38321088, 2024). "Further analysis revealed that PSMA7 amplification was the most frequent genetic alteration event conferring adverse prognosis in various cancers." (PMID 38321088, 2024). "These discoveries suggested again that 20q13.33 harboring PSMA7 among others was plausibly a novel amplicon that frequently existed in human cancers." (PMID 38321088, 2024). "Consistent with the strong positive correlation between PSMA7 amplification and gene expression, elevated PSMA7 expression was observed in 20 of 33 types of cancers with a close link to adverse outcomes in certain tumors." (PMID 38321088, 2024). "The data above generally described the drug-response pattern of abnormal PSMA7 in cancer cell lines that need further exploration in future work." (PMID 38321088, 2024). "Given that the aberrant PSMA7 expression possibly adversely influenced the clinical outcome of various cancers, we then explored the possible molecular mechanism linking high expression of PSMA7 to tumorigenesis." (PMID 38321088, 2024). "The current in-depth pan-cancer analysis refines our understanding of the crucial oncogenic role of copy number amplifications at PSMA7 loci at the novel chromosome amplicon 20q13.33 across different tumors." (PMID 38321088, 2024). "Taken together, these data showed that PSMA7 overexpression frequently occurred in most human cancers." (PMID 38321088, 2024). "Then we at a pan-cancer level systematically explored the status of amplification and expression of the PSMA7 gene and their clinical significances in terms of prognosis and potential therapeutic opportunity." (PMID 38321088, 2024). "With this regard, the dependency of tumor cells on PSMA7 was evaluated by the genome-scale CRISPR-Cas9 knockout screens in the 1095 cancer cell lines extracted from the Depmap48 database." (PMID 38321088, 2024). "Thus, PSMA7 silencing may cause cancer cells to enter apoptosis." (PMID 28523434, 2017). "Psma7 is negatively correlated with interferon based response to viral antigens, furthermore Psma7 depletion inhibits cancer growth, being heavily involved in cell cycle and transcription control." (PMID 25925689, 2015). "To uncover the drug-response landscape of cancers expressing upregulated PSMA7, we analyzed the potential connection of drug sensitivity with this gene mRNA expression across pan-cancers based on the drug sensitivity in cancer (GDSC) and cancer therapeutics response portal (CTRP) databases." (PMID 38321088, 2024).
cancer (continued). "Collectively, these data suggested that copy number amplification of PSMA7 might lead to gene overexpression in human cancers." (PMID 38321088, 2024). "Notably, PSMA7, one of the proteasome family members, achieved the highest correlation score of 0.452 with cancer, suggesting the crucial oncogenic role of PSMA7 in 20q13.33." (PMID 38321088, 2024). "Since PSMA7 overexpression was validated due to amplification in clinical samples with different types of cancers, we further asked whether PSMA7 amplification showed poor response to these resistant agents, for instance, the first-ranking compound TPCA-150." (PMID 38321088, 2024). "S14), highlighting the promising therapeutic value of this agent for PSMA7-related cancers." (PMID 38321088, 2024). "Among those genes at 20q13.33, PSMA7 was found with the strongest correlation with cancers." (PMID 38321088, 2024). "However, the precise roles and relevant mechanisms of PSMA7 across human cancers remained less well understood." (PMID 38321088, 2024). "Additionally, c-ABL-mediated upregulation of PSMA7 led to the formation of alternative proteasome isoforms of PSMA7-PSMA7, eventually influencing cancer cell fitness." (PMID 38321088, 2024). "Besides, almost all of these cell lines had high half maximal inhibitory concentrations (IC50) and poor area-under-the-curve (AUC) sensitivity scores for TPCA-1, suggesting that amplification of PSMA7 might protect cancer cell lines from TPCA-1 treatment." (PMID 38321088, 2024). "In addition, PSMA7 was essential for the growth of almost 1095 cancer lines." (PMID 38321088, 2024). "Mechanistically, aberrant PSMA7 most probably influenced the proteasome and protease-related pathways to promote tumorigenesis and might be antagonized by several compounds, e.g., Docetaxel in relevant cancers." (PMID 38321088, 2024). "Although PSMA7-resistant compounds accounted for the majority, we found six compounds with negative R-values and FDR ≤ 0.05 in GDSC that might be sensitive to cancers with elevated PSMA7 expression." (PMID 38321088, 2024). "The PSMA7 depletion resulted in significantly negative screen scores (concentrate range: − 2.0 to − 3.0) in the majority of types of cancers, highlighting that PSMA7 was required for tumor cell growth as previously reported." (PMID 38321088, 2024). "Therefore, we inferred that the chromosome amplicon 20q13.33 might be the work unit in which PSMA7 but at least not LAMA5 functioned as a cancer-promoting factor." (PMID 38321088, 2024). "To comprehensively explore the genetic alterations of the PSMA7 gene locus rather than CNA1,2, we conducted a genetic alteration survey of PSMA7 across 32 types of TCGA cancers via the cBioPortal approach." (PMID 38321088, 2024).
tumor (10 papers, 2017 to 2025). "A subset of tumor cells expressing DPPA4 and PSMA7 showed high stemness, enhanced self-renewal, and association with metastasis." (PMID 41203637, 2025). "Knockdown of DPPA4 and PSMA7 significantly reduced the size of tumor spheres in both cell lines." (PMID 41203637, 2025). "Notably, we discovered that PSMA7 expression displayed a positive link to TMB and MSI in diverse tumors, figuring out the potential role of PSMA7 in DNA damage repair for tumor cells." (PMID 38321088, 2024). "Therefore, genes VEGFA, ANXA1, HSP90B1, PSMA7, PRDX6, and PPP1CB may be new targets for anti-tumor effects in the future." (PMID 36741702, 2022).
infection (2 papers, 2016 to 2019). The state of being infected such as from the introduction of a foreign agent such as serum, vaccine, antigenic substance or organism. "The expression profiles of the negative regulators PSMA7 and PCBP2 were similar at both the RNA and protein levels, and increased slowly during infection." (PMID 30642258, 2019).
psychiatric disorder (1 paper, 2015). A disorder characterized by behavioral and/or psychological abnormalities, often accompanied by physical symptoms. "Only one study has shown a putative role of proteasomal PSMA7, PSMD9 and PSMD13 genes in the susceptibility to an antidepressant response, and sparse data are available regarding the potential alterations in proteasome expression in psychiatric disorders such as MDD." (PMID 26624926, 2015).
PSMA7 also shares sentences with these, for which no sentence is quoted: inflammatory bowel disease (4 papers); depression (3); neutropenia (2); prostate carcinoma (2); anemia (1); asthma (1); atherosclerosis (1); blood disorders (1); breast tumors (1); Cachexia (1); cervical squamous cell carcinoma (1); cholangiocarcinoma (1); Cognitive impairment (1); cystinosis (1); dermatitis herpetiformis (1); diffuse large B-cell lymphoma (1); digestive diseases (1); endocervical adenocarcinoma (1); epidermolysis bullosa acquisita (1); esophageal carcinoma (1); genetic disorders (1); glioblastoma (1); glioma (1); globoid cell leukodystrophy (1); head and neck squamous cell carcinoma (1); hepatitis C (1); hypertrophic cardiomyopathy (1); leukemia (1); lysosomal storage disorders (1); metachromatic leukodystrophy (1).
A further 12 diseases each share a sentence with PSMA7 in 1 paper.